FKBP1C (FKBP prolyl isomerase family member 1C)
Description:
Catalyzes the cis-trans isomerization of proline imidic peptide bonds in oligopeptides.
Synonyms: bA184C23.2
Tractability: Small molecule: it belongs to a druggable protein family. PROTAC: ubiquitination databases record sites on it.
Gene: Protein-coding gene on chromosome 6 (63,211,469 to 63,213,027, forward strand). Ensembl gene ENSG00000198225.
Subcellular location (Human Protein Atlas): Golgi apparatus; Basal body; Cytosol; Primary cilium
Gene Ontology:
Molecular function: peptidyl-prolyl cis-trans isomerase activity
Biological process: protein folding; regulation of cardiac muscle contraction by regulation of the release of sequestered calcium ion
Cellular component: sarcoplasmic reticulum membrane
Genetic constraint (gnomAD): Loss-of-function variants: 6 observed, 5.43 expected, observed/expected ratio (o/e) 1.1, 90% interval 0.59 to 1.84. That is too few expected variants to judge how well the gene tolerates losing a copy. Missense variants: 115 observed, 114.12 expected, observed/expected ratio (o/e) 1.01, 90% interval 0.87 to 1.18. Synonymous variants: 43 observed, 42.31 expected, observed/expected ratio (o/e) 1.02, 90% interval 0.8 to 1.31.
Homologues: Orthologues: macaque FKBP1A (95% identical), guinea pig Fkbp1a (94% identical), mouse Fkbp1a (93% identical), rat Fkbp1a (87% identical), dog FKBP1A (82% identical), Drosophila melanogaster Fkbp12 (71% identical), Caenorhabditis elegans fkb-5 (42% identical), Caenorhabditis elegans fkb-4 (38% identical). Paralogues in human: FKBP1A (95% identical), FKBP1B (80% identical), FKBP10 (46% identical), FKBP4 (44% identical), FKBP9 (44% identical), FKBP2 (44% identical), FKBP3 (44% identical), FKBP5 (44% identical), FKBP11 (35% identical), FKBP14 (32% identical), FKBP15 (32% identical), FKBP7 (31% identical), and 6 more.
Diseases named in the same sentence as FKBP1C in open-access papers:
FKBP1C is named in the same sentence as 1 disease in open-access papers, as found by Europe PMC text mining. Sharing a sentence is not in itself a finding about the gene and the disease.
FKBP1C shares sentences with these, for which no sentence is quoted: Pituitary adenoma (1 paper).